IGF1 (insulin like growth factor 1)
Diseases named in the same sentence as IGF1 in open-access papers (continued):
Sharing a sentence is not in itself a finding about the gene and the disease.
intrauterine growth restriction (51 papers, 2007 to 2025). "These relationships between gene expression, promoter methylation and birthweight suggest that the epigenetic control of IGF1 expression has a causative role in the pathogenesis of fetal growth restriction." (PMID 26823688, 2016). "Similarly, an inverse association between SIRT1 and IGF-1 has also been observed in cases of intrauterine growth restriction (IUGR)." (PMID 39062007, 2024). "In the pathophysiology of fetal growth restriction, the reduction of insulin and of IGF-1 levels causes a decrease in the proliferation of renal cells, which may affect the pressure of glomelluric capillaries." (PMID 30939608, 2019). "Moreover, maternal malnutrition alters methylation of the GH responsive promoter 2 of the IGF-1 gene and intrauterine growth restriction is associated with sustained hypermethlyation of the IGF-1 promoter in rats thereby amplifying the signaling impairment of GH in the neonate." (PMID 25774292, 2015). "Pregnancies that are complicated by fetal macrosomia or intrauterine growth restriction (IUGR) have either high or low fetal IGF-1 concentrations, respectively." (PMID 36091374, 2022). "One of its adverse outcomes is fetal growth restriction, an alteration in development due to decreased IGF-1 levels." (PMID 36138743, 2022). "Loss-of-function mutations in IGF1R have been reported in children presenting with intrauterine growth restriction, short stature, and elevated IGF-1 levels." (PMID 36530175, 2022). "Despite the fact that ksr2−/− mice are born normal in size, the effects of KSR2 disruption show a striking similarity to the effects of intrauterine growth retardation (IUGR) on the IGF-1/IGFBP axis." (PMID 27561547, 2016). "Another example of epigenetics governed by histones and IGFs is intrauterine growth restriction (IUGR), where a decrease in postnatal IGF‐I mRNA variants is associated with histone 3 tri‐methylation of lysine 36 at the igf1 gene (H3Me3K36)." (PMID 27061217, 2016). "It was shown that the babies with intrauterine growth retardation showed relatively increased GH and low IGF-1 and IGFBP-3 concentrations, relatively low leptin, and increased ghrelin values." (PMID 24228030, 2013). "Among these, growth retardation is most penetrant (90%), manifesting as both prenatal intrauterine growth restriction (IUGR; 53%) and postnatal short stature (90%), as well as low serum insulin-like growth factor-1 (8 of 11 tested, 73%) and growth hormone deficiency (7 of 7 formally tested)." (PMID 40926810, 2025). "Possibly, IGF-1 supplementation is relevant to consider for subgroups of very/extremely preterm infants with additional complications such as being born after fetal growth restriction and inflammation, negatively affecting both IGF-1 production and immune development." (PMID 37648745, 2024). "Importantly, we demonstrate that delivery of IGF-1 via the nanoparticle was able to express sufficient transgene to restore normal fetal growth in a mouse model of placental insufficiency and fetal growth restriction." (PMID 26473479, 2015). "Interestingly, high IGFBP-4 concentrations have previously been linked to fetal growth restriction in human gestation, and less proteolytic cleavage might be due to higher IGFBP-4 and lower IGF-1 levels." (PMID 29946296, 2018). "One phenotype exhibits significant placental and fetal growth restriction (PI-FGR), impaired placental nutrient transport, and significant reductions in umbilical insulin and IGF1." (PMID 37374044, 2023). "Hepatic IGF-1 mRNA levels largely impact serum IGF-1 levels and are heavily modulated by epigenetics in the setting of intrauterine growth restriction (IUGR)." (PMID 22548154, 2012). "In cases of intrauterine growth restriction (IUGR), the expression of Klotho protein in maternal venous blood, umbilical cord blood, and placental tissue are reduced, accompanied by changes in GH, IGF-1, and IGFBP." (PMID 40831795, 2025).
intrauterine growth restriction (continued). "Previous work in our laboratory demonstrated that over-expression of human insulin-like growth factor -1 (hIGF-1) in the placenta corrects fetal weight deficits in mouse, rat, and rabbit models of intrauterine growth restriction without changes in placental weight." (PMID 24019972, 2013).
thyroid cancer (51 papers, 1995 to 2026). "IGF-1 is positively associated with the risk of developing thyroid cancer." (PMID 36755926, 2023). "The association between height and thyroid cancer incidence could be explained partially by the effect of insulin‐like growth factor (IGF‐1)." (PMID 29577664, 2018). "Also, the serum IGF1 levels were associated with the histologic characteristics of thyroid cancer." (PMID 32851683, 2020). "From a mechanistic point of view, M2-like TAM-secreted IGF1/IGF2 activated the IR-A/IGF1R/AKT signaling in thyroid cancer cells, thereby sustaining the malignant phenotype." (PMID 38892104, 2024). "In fact, most thyroid cancer cells overexpressed IR, which can amplify the biological effects of IGF-1 through forming hybrid IR/IGF-1R receptors that will bind IGF-1 with high affinity." (PMID 33669363, 2021). "In thyroid cancer, IGF1-mediated activation of Akt promotes FoxO1 export from the nucleus, inhibition of FoxO1-mediated transcriptional activation of target genes like CDKN1B (p27KIP1) cell cycle inhibitor, thus promoting cell proliferation." (PMID 33673232, 2021). "The expression of the IGF-1 system is enhanced in thyroid cancer (especially in PTC) compared to other thyroid diseases." (PMID 34640473, 2021). "Although IGF-1 and IGF-1R are both expressed in normal thyroid tissue and thyroid cancer tissue, compared with normal tissue, IGF-1 and IGF-1R are overexpressed in TCs." (PMID 33815885, 2021). "Univariate logistic regression analysis showed that serum 25(OH)D, IGF-1 and PDGF were significantly associated with the risk of thyroid cancer." (PMID 32711436, 2020). "Multivariate analysis demonstrated that serum 25(OH)D (OR=0.578, 95%CI= 0.426-0.783), IGF-1 (OR=1.019, 95%CI= 1.010-1.029) and PDGF (OR=1.007, 95%CI= 1.004-1.009) were considered independent risk factors for thyroid cancer (P<0.001, for all)." (PMID 32711436, 2020). "The Multivariate analysis also demonstrated that serum 25(OH)D (OR=0.578, 95%CI= 0.426-0.783), IGF-1 (OR=1.019, 95%CI= 1.010-1.029) and PDGF (OR=1.007, 95%CI= 1.004-1.009) were considered independent risk factors for thyroid cancer (P<0.001, for all)." (PMID 32711436, 2020). "Multivariate analysis demonstrated that serum 25(OH)D, IGF-1 and PDGF were considered independent risk factors for thyroid cancer." (PMID 32711436, 2020). "IGF-1 plays an important role in the formation and development of thyroid nodules, including thyroid cancer and thyroid adenoma." (PMID 31555212, 2019). "Another study found a positive correlation between tumor size and IGF-1 involvement in thyroid cancers." (PMID 29081797, 2017). "Many recent studies have reported an increase in IGF-1 production both in benign and malignant thyroid tumors." (PMID 29081797, 2017). "One possible explanation of the effect of height in thyroid carcinoma could be the role of insulin-like growth factor-1 (IGF-1)." (PMID 37772697, 2023). "Some papers concern studies of one of the IGF1 isoforms and its derivatives (e.g., IGF1Ec, Ec peptide) in vivo and in vitro, or studies conducted only considering selected cancers (e.g., prostate cancer, thyroid cancer, NENs)." (PMID 32977489, 2020). "Increased IGF-1 stimulation may increase carcinogenesis and act with other initiating factors to promote progression of thyroid cancer from an occult to a clinically relevant stage." (PMID 25329702, 2014). "We have correlated the morphological features of 30 human thyroid carcinomas with the cellular localisation of insulin-like growth factor 1 (IGF-1) mRNA and IGF-1 receptor peptide using in situ hybridisation with digoxigenin-labelled oligoprobes and immunohistochemistry." (PMID 7547225, 1995). "However, IGF-1 plays an important role in the development and regulation of postnatal growth, with taller people having increased levels of IGF-1 during childhood and adolescence, leading possibly to increased risk of thyroid cancer in adult life 8,24." (PMID 37772697, 2023).
thyroid cancer (continued). "As thyroid follicular epithelial cells express insulin-like growth factor 1 (IGF-1) receptors and IGF-1 is an important factor for promoting replication and reducing apoptosis of these cells, IGF-1 could potentially be linked to the promotion of thyroid cancer in acromegalic patients." (PMID 32333269, 2020). "IGF1 is mainly produced locally in either a paracrine or autocrine manner and although it is present both in normal and in thyroid cancer tissues, IGF1 and its receptor IGF-1R are found to be overexpressed in thyroid cancer cell lines." (PMID 39199391, 2024). "Overexpression of IGF-1, IGF-1R, IGF-2 and insulin receptor (IR) can be seen in the early stage of thyroid cancer." (PMID 35711846, 2022). "The current study provides an evidence that serum levels of 25(OH) D, IGF-1 and PDGF are significantly different in thyroid cancer and benign nodule cases compared to normal subjects." (PMID 32711436, 2020). "Thyroid cancer (TC) is a common malignant tumor, however the role of total vitamin D: 25(OH)D, Platelet Derived Growth Factor (PDGF) and Insulin Like Growth Factor 1 (IGF-1) in the development of TC is still unclear." (PMID 32711436, 2020). "The acromegalic patients with differentiated thyroid cancer were older and more often female, with similar levels of GH/IGF-1 compared with acromegalic patients without thyroid cancer." (PMID 37435457, 2022). "As thyroid follicular cells express IGF-1 receptors and IGF-1 is a well recognized growth factor for thyrocites, it may be speculated that IGF-1 has a potential role in the development of thyroid cancer in acromegalic patients." (PMID 25127456, 2014).
ischemic heart disease (49 papers, 2007 to 2025). "Low levels of IGF-1 were associated with increased risk for angiographically confirmed coronary heart disease in cross-sectional and prospective studies and predicted death therefrom." (PMID 33686453, 2021). "In a population study of elderly individuals, decreased serum Igf1 expression was shown to be a risk factor for mortality after ischemic heart disease." (PMID 34364390, 2021). "SNPs rs1520220, rs2946834, and rs5742694 in IGF1 had continuously been linked to cancer prognosis, as well as coronary artery disease." (PMID 32150843, 2020). "IGF-1 levels were also positively associated with coronary artery disease in a cross-sectional study of 6773 German adults." (PMID 32548700, 2020). "Other cross-sectional and nested case–control studies showed a null association between IGF-1 levels and coronary artery disease (167–1013 cases) and cerebrovascular events (273 cases)." (PMID 32548700, 2020). "Low free IGF-1 was also associated with increased risk of carotid plaque and coronary artery disease." (PMID 30469478, 2018). "Another paper analyzed the association between polymorphisms in the IGF1 gene and coronary arteriosclerosis." (PMID 27835972, 2016). "Nine biomarkers outcomes were collected at 46 years of age: body mass index (BMI), blood pressure, total and high-density cholesterol, triglycerides, glycated haemoglobin, C-reactive protein (CRP), insulin-like growth factor 1 and we computed the 10-year risk for coronary heart disease." (PMID 34583963, 2022). "Consistently, an observational study indicated that low circulating IGF-1 and high IGFBP-3 levels were significantly associated with increasing the risk of developing ischemic heart disease in a primary prevention population." (PMID 35332212, 2022). "Insulin-like growth factor-1 (IGF-1) has been associated with both protective and detrimental effects on the development of ischemic heart disease." (PMID 34851758, 2021). "CCL3, CCL18, CXCL12/SDF-1, CXCL16, IGF1 and IL10 have been linked to pro-angiogenesis and/or coronary artery diseases." (PMID 23496821, 2013). "IGF1 and IGFBP1 have been found to associate positively with all cause and ischemic heart disease mortality in the elderly Rancho Bernardo cohort." (PMID 24373343, 2013). "These are positive findings suggesting that IGF-1 has a beneficial cardioprotective role in ischemic heart disease." (PMID 21651821, 2011). "Circulating levels are therefore not necessarily directly related to the hypothesized pathophysiological mechanisms by which IGF-1 and PAPP-A are implicated in development of coronary artery disease." (PMID 31963719, 2020). "Epidemiological studies also confirmed that low baseline levels of IGF1 increased the risk of fatal ischemic heart disease among elderly men and women independent of prevalent cardiovascular risk factors." (PMID 32974138, 2020). "Since stem cell therapy has emerged as a promising method for treatment of ischemic heart disease, IGF-1 and bFGF could possibly help BMSCs function better based on our preliminary result." (PMID 27419126, 2016). "Furthermore, coronary heart disease (CHD) patients have been found to have significantly higher serum concentrations of IGF-1, a feature that is believed to contribute to coronary atherosclerosis 31,32." (PMID 26039631, 2015). "In addition, lower serum iron concentrations are associated with higher concentrations of proinflammatory markers and lower concentrations of the cardioprotectant insulin-like growth factor-1 in ischemic heart disease." (PMID 25100442, 2014). "Additionally, low levels of insulin-like growth factor 1 (IGF-I) have been associated with both decreased fetal growth (which may result in SGA/LBW) and increased ischemic heart disease mortality in the general population." (PMID 39832115, 2025).
ischemic heart disease (continued). "A study conducted in Kuwait reported significantly lower levels of IGF-1 and IGFBP-3 in patients with coronary heart disease (CHD) and significant correlation between the level of IGFBP-3 and some metabolic markers including cholesterol, triglyceride (TG) and high-density lipoprotein (HDL)." (PMID 34394011, 2021).
osteoarthritis (48 papers, 2006 to 2026). A noninflammatory degenerative joint disease occurring chiefly in older persons, characterized by degeneration of the articular cartilage, hypertrophy of bone at the margins and changes in the synovial membrane. "Recently, there has been increased attention to the association between IGF-1 and osteoarthritis (OA)." (PMID 39050250, 2024). "For instance, in horses with mild osteoarthritis, clinical improvement was statistically associated with content of not only IL-1Ra but also IGF-1 in ACS." (PMID 33681323, 2021). "Several reports indicate that age reduces chondrocyte responsiveness to pro-anabolic factors such as insulin-like growth factor 1 (IGF-I), and increases susceptibility to osteoarthritis, indicating a complicated interplay between aging and inflammation." (PMID 28122611, 2017). "Eleven metabolites were found to have a causal association with an increased risk of osteoarthritis, including isovaleryl carnitine, taurocholate, kynurenine, acetaminophen 4-sulfate, homocysteine, serum iron, transferrin saturation, insulin-like growth factor-1, serum copper, and serum zinc." (PMID 39172202, 2024). "This research is pioneering in incorporating spinal osteoarthritis into the investigation of IGF-1 and various types of OA, with BMI serving as a novel mediating variable." (PMID 39050250, 2024). "CALC2 level was measured after in vitro cleavage of recombinant type II collagen with bone morphogenetic protein-1 (BMP-1) and treatment of ex vivo human osteoarthritis (OA) cartilage explant model (HEX) with insulin-like growth factor-1 (IGF-1)." (PMID 36613894, 2022). "More importantly, the apoptosis triggered by S100A6 can be offset by the PI3K/AKT pathway inhibitor and activator (LY294002 and IGF‐1), the values of Caspase‐3 activity and apoptosis index became close to the untreated osteoarthritis group." (PMID 33942537, 2021). "Other elements and side products which further increase cartilage degradation and play a role in osteoarthritis include insulin-like growth factor 1 (IGF-1), and chondrodegradative enzymes." (PMID 34071929, 2021). "Several growth factors also play important roles in normal cartilage metabolism, where insulin-like growth factor-1 (IGF1) promotes the synthesis of ECM representing an outstanding growth factor for gene therapy of osteoarthritis." (PMID 31149016, 2019). "Human cartilage explants from replaced osteoarthritis knees were cultured for ten weeks in the presence of growth factors, insulin-like growth factor 1 (IGF-1) or recombinant human fibroblast growth factor 18 (rhFGF-18)." (PMID 30404167, 2018). "Osteoarthritis changes in acromegalic patients with long duration of disease is a well-known phenomenon due to exposure to high GH and IGF1 levels." (PMID 25600246, 2015). "In one study, patients with DISH and those with osteoarthritis had elevated levels of insulin and growth hormone, however, the level of IGF-1 was higher in patients with DISH than in those with osteoarthritis." (PMID 23049626, 2012). "Bone homeostasis is regulated through osteoclast resorption and osteoblast formation, mediated by cytokines such as TGF-β and IGF-1.49,50 Overactivity of osteoclasts can disrupt this balance, leading to uncoupling and pain in degenerative diseases like osteoarthritis and LBP." (PMID 41571628, 2026). "While some case-control studies have not established a link between increased IGF-1 levels and heightened osteoarthritis (OA) risk." (PMID 39050250, 2024). "However, the application of novel therapeutics, celecoxib-coated microspheres, local administration of IGF-1 and activated chondrocytes following surgical debridement of SBCs hinders the expansion of SBCs and prevents the progression of osteoarthritis." (PMID 36769464, 2023).